PPARA (peroxisome proliferator activated receptor alpha)
Diseases named in the same sentence as PPARA in open-access papers (continued):
Sharing a sentence is not in itself a finding about the gene and the disease.
Hepatic steatosis (continued). "PPARα agonists and fatty acids elevated during fasting and hepatic steatosis could prevent dicarboxylic acid formation through induction of the genes including ω-oxidation CYP4A and peroxisomal β-oxidation." (PMID 20300478, 2009). "Moreover, alcohol‐induced overexpression of insulin‐like growth factor binding protein 7 (IGFBP7) further exacerbates hepatic steatosis by suppressing peroxisome proliferative activated receptor, alpha (PPARα) signaling and indirectly modulating the transcription of genes involved in lipid uptake." (PMID 41362700, 2025). "This could be attributed to the protective role of MSCs-Exo+EVOO against hepatic steatosis via promoting lipid oxidation related factors, PPARα, CPT-1, and ACOX, involved in fatty acid oxidation and suppressing synthesis of fatty acid via controlling PPARα, CPT-1A, SREBP-1, and FAS expression." (PMID 41144456, 2025). "Additionally, monounsaturated fatty acids (MUFAs) may activate PPARα, a key regulator of lipid metabolism and generator of peroxisomes, thereby reducing hepatic steatosis and preventing metabolic stress." (PMID 41009545, 2025). "Our study supports the model that HuR suppresses the expression of fatty acid catabolism genes by blocking their pre-mRNA processing, which may partially explain the mild effects of PPARα agonists in treating fatty liver diseases in humans as compared with studies in mice." (PMID 40981382, 2025). "Importantly, the PPARα play a pivotal role in regulating hepatic lipid metabolism, fatty acid oxidation, and oxidative stress, and its abnormalities may lead to hepatic steatosis, and liver cancer." (PMID 38395901, 2024). "Therefore, N800 treatment may induce hepatic steatosis by impairing both Pparα-mediated mitochondrial β-oxidation and Foxa1/Srebp1c-mediated lipid metabolism gene expressions." (PMID 39061900, 2024). "In addition, VD supplementation may alleviate hepatic steatosis by regulating lipid uptake and β-oxidation via the PPARα signaling pathway." (PMID 37033263, 2023). "Therefore, in male PPARα−/− mice, the loss of Pparα expression leads to the compensatory upregulation of the Pparγ and the regulation of the expression of genes with PPRE, resulting in the development of fatty liver." (PMID 36140300, 2022). "Hence, PPARα activation is central to the remission of hepatic steatosis and NAFLD progression." (PMID 35528835, 2022). "We concluded that BCPs treatment could ameliorate hepatic steatosis via the PPARα/CPT1 pathway in HFD-induced obese rats.Moreover, the degradation of DAG occurs through the phosphorylation and cytidine diphosphate diacylglycerol (CDP-DAG) pathway by DGK and EPT1, generating PA and PE, respectively." (PMID 35990329, 2022). "In this study, the injection of HFD-induced obese mice with MS-275 prevented hepatic steatosis by reducing de novo lipogenesis and increasing lipolysis and mitochondrial oxidation, by increasing the expression of oxidation-related genes, such as PPARα, MCAD, CPT1b, and FGF21." (PMID 36077368, 2022). "It is well established that the HFD can induce hepatic steatosis in rodents through an increase in the expression of transcription factors like SREBP1c, a major activator of lipogenic genes and peroxisome proliferator-activated receptor alpha (PPARα), and the enzymes FAS and ACC in mouse livers." (PMID 34406209, 2021). "Therefore, the combined actions of circRNA_021412, circRNA_0046366, and circRNA_0046367 to suppress the miRNAs that control PPARA signaling may be an alternative therapeutic target to reduce hepatic steatosis." (PMID 35052690, 2021). "Moreover, palmitoleic acid contained in krill oil may contribute not only to the positive effects of this marine oil on glucose homeostasis and insulin sensitivity, but also on liver steatosis due to its stimulatory effects on PPARα and AMPK activation." (PMID 33572810, 2021).
Hepatic steatosis (continued). "Importantly, the present study indicates a possible mechanism whereby the combination of GCN2 deficiency and exercise may suppress the initiation of HFD-induced hepatic steatosis more effectively by activation of the AMPK/SIRT1/PPARα pathway in the liver." (PMID 33299856, 2020). "Nrf2 activation ameliorates methionine- and choline-deficient (MCD) diet-induced hepatic steatosis, inhibiting Cluster of differentiation 36 (CD36), Fibroblast growth factor 21 (Fgf21), and PPARα expression in the liver of mice, whereas Nrf2 deletion increases PPARα expression." (PMID 33066023, 2020). "As a nuclear transcription factor, PPARα could mediate the effect of GLP-1 in alleviating hepatic steatosis by differentially regulating the expression of its target genes, including acetyl CoA carboxylase and carnitine palmitoyl transferase la both in vitro and in vivo." (PMID 33746742, 2020). "Thus, the RAGE/PPARα regulatory axis might be a promising therapeutic target for aging‐related fatty liver disease." (PMID 32936538, 2020). "Furthermore, miR-34a regulates lipid-metabolism gene expression, specifically targeting liver peroxisome proliferation-activator receptor α (PPARα) and inhibiting very low-density lipoprotein secretion, while promoting hepatic steatosis and hypolipidemic effects in a HNF4-dependent manner." (PMID 30931332, 2019). "We assessed whether MD001, as a dual agonist of PPARα/γ, may alleviate fatty liver in db/db mice." (PMID 30733541, 2019). "This study hypothesized that Tungrymbai, a well-known fermented soybean food commonly consumed in the state of Meghalaya, India, could prevent the intracellular lipid accumulation, impaired lipid oxidation, and hepatic steatosis via regulating AMPK/SREBP/PPARα signaling pathway." (PMID 29968750, 2018). "Importantly, PPARα knockout exacerbated alcohol-induced fatty liver and liver injury, while PPARα agonist administration improved liver pathologies in mice induced by chronic alcohol exposure, suggesting that PPARα inhibition is a key mechanism during the development of ALD." (PMID 29020055, 2017). "In conclusion, attenuation of the hepatic steatosis by pioglitazone may be conferred by refining insulin sensitivity, intensifying cytosolic lipolysis, β-oxidation and lipophagy-mediated lysosomal lipolysis in a manner of PPARα/γ dependently." (PMID 28831172, 2017). "Of note, hepatic steatosis is usually associated to liver n-3 long-chain polyunsaturated fatty acid depletion, thereby leading to substantial enhancement in hepatic sterol regulatory element binding protein (SREBP)-1c/PPARα ratio that favors de novo lipogenesis over fatty acid β-oxidation." (PMID 29244870, 2017). "Interestingly, FGF21 overexpression partially restored the expression of PPARα and its target genes, Acox1, Hmgcs2 and Cpt1a in Creb3l3−/− mice, which might have helped to improve the hepatic steatosis." (PMID 27301791, 2016). "Thus we hypothesized that E2F8 transcription factor mediated FABP3 transactivation might be a downstream of PPARα in the development of hepatic steatosis." (PMID 26052340, 2015). "In this study, we investigated the hypothesis that the nuclear receptor PPARα may be involved in the beneficial activities of palmitoleic acid in attenuating the development of HFD-induced hepatic steatosis and inflammation and disruptions of glucose homeostasis." (PMID 25147439, 2014). "On the contrary, drugs that reduce hepatic steatosis, such as PPARα regulators, should be considered with caution in clinical liver surgery, as other studies indicate that genetic or pharmacologic approaches that reduce lipid accumulation may also hinder liver regeneration." (PMID 22675337, 2012). "In addition, mice deficient in PPARα failed to activate peroxisomal gene expression following prolonged starvation and developed severe hepatic steatosis accompanied by lower ketones levels in circulation." (PMID 23133608, 2012).
Hepatic steatosis (continued). "Other PPARα agonists (e.g., Wy 14 643) administered to mice fed an HF diet failed to prevent liver inflammation, but could improve other metabolic parameters such as hyperglycemia and hepatic steatosis." (PMID 23024649, 2012). "It has been reported that PPARα activation upregulates its target genes (LPL, ACOX1, and CPT-1a) expression, enhancing lipid degradation and fatty acid oxidation, which ameliorates hepatic steatosis, dyslipidemia, and insulin resistance." (PMID 39942052, 2025). "TAC ameliorates hyperlipidemia and hepatic steatosis through dual modulation of AMPK/SREBP-1c-mediated lipid synthesis and PPARα/LXRα-driven lipolysis, presenting a multifaceted therapeutic approach for metabolic disorders." (PMID 41244823, 2025). "mTOR inhibitors (e.g., everolimus) inhibit hepatic lipid metabolism genes (e.g., PPARα, AMPK), exacerbating hepatic steatosis in T2DM patients." (PMID 40963676, 2025). "Methyl ferulate can also promote the expression of PPARα and CPT1 by upregulating SIRT1, significantly inhibiting ethanol-induced hepatic steatosis." (PMID 41154556, 2025). "Activation of PPARα up-regulates the transcription of a range of genes related to FAO in hepatocytes, thereby reducing hepatic steatosis." (PMID 39911797, 2025). "In contrast, TRPV1−/− mice exhibited markedly reduced levels of both PPARα and PGC-1α, consistent with the severe hepatic steatosis observed in histological analyses (H&E and Oil Red O staining)." (PMID 40864772, 2025). "Studies also proved that HO-1 alleviates oxidative stress and reverses the adipocyte phenotype and hepatic steatosis by upregulating SIRT-1 and PPARα." (PMID 38846488, 2024). "Quercetin enhanced PPARα and CPT-1 expression and decreased hepatic steatosis by increasing fatty acid oxidation." (PMID 39458470, 2024). "Hepatic steatosis is a key component of NAFLD pathophysiology, requiring the coordination between peroxisome proliferator-activated receptor alpha (PPARα) and PPARγ to balance fatty acid synthesis and oxidation." (PMID 39872862, 2024). "Although the underlying mechanisms of DHM in the prevention and treatment of NAFLD are complex, our findings indicate that DHM improves hepatic steatosis and IR via AMPK/PGC-1α or PPARα-inducing autophagy in a rat model and steatotic hepatocytes." (PMID 38532480, 2024). "Despite being a substrate of both PPARα and PPARγ, LDT409 was crucial for promoting hepatic fatty acid oxidation and reducing hepatic steatosis in HFD-fed mice." (PMID 38763495, 2024). "miR6262 promoted an extensive inhibition of RXRA and PPARA mRNA levels in basal (untreated with FFA) cells and HepG2 cells exposed to FFA to mimic hepatic steatosis." (PMID 39339747, 2024). "Thus, AMPK and PPARα may be major targets for the prevention of hepatic steatosis." (PMID 39458470, 2024). "In current work, we found that NOB intake could reduce hepatic TG and TC content and improve hepatic steatosis by lowering the expression of genes related to lipogenesis (Srebp-1c, Scd-1, and Fas) and increasing the expression of genes involved in lipid oxidation (Pparα)." (PMID 36985541, 2023). "According to the current study, rats fed an HFD had significantly lower levels of PPARα and CPT-1, which contributed to the pathogenesis of fatty liver." (PMID 37173727, 2023). "We have shown that this newly discovered molecule has an exceptional ability to inhibit hepatic steatosis by suppressing oxidative stress and inflammation and by acting on the SREBP1, PPARα, Nrf2, and NF-κB signaling pathways." (PMID 38004149, 2023). "The molecular mechanisms involved in the alcohol-induced fatty liver include crosstalk between the upregulation of SREBP-1c, ACC-1, and FASN and the downregulation of PPARα, which was evident in our reported data in the ALD group." (PMID 36959348, 2023).
Hepatic steatosis (continued). "A recent study demonstrated that the deletion of hepatic Pparα in mice results in enhanced liver steatosis because of the impaired oxidation of FFA, underscoring the relevance and potential of hepatocyte PPARα as a drug target for NAFLD." (PMID 37047034, 2023). "In another study, AAV-miR-20b administration induced hepatic steatosis and reduced FA oxidation in HFD-fed mice, possibly by decreasing the level of PPARα." (PMID 37834101, 2023). "In conclusion, ESGA prevents NAFLD in HFD-fed rats by attenuating hyperlipidemia, hepatic steatosis, oxidative stress, and inflammation by acting locally on Nrf2, NF-κB, SREBP1, and PPARα transcription factors." (PMID 38004149, 2023). "PPARα-null mice showed advanced fatty liver and steatohepatitis, while patients with NASH demonstrated a reduction in hepatic PPARα expression." (PMID 37233667, 2023). "From a mechanistic point of view, PM2.5 exposure can inhibit the expression of PPARα and PPARγ, impairing the regulation of glucose and lipid metabolism, FAO, and immune response, thus leading to hepatic steatosis, inflammation, and IR." (PMID 37242221, 2023). "The study aimed to explore the association of serum 25(OH)D3 and hepatic steatosis in non-alcoholic fatty liver disease (NAFLD) patients and to determine whether the effect of vitamin D (VD) is mediated by activation of the peroxisome proliferator-activated receptor α (PPARα) pathway." (PMID 37033263, 2023). "In HFD model, liver-specific Sirt1 knockout impaired PPARα/PGC-1α signaling and reduced fatty acid oxidation, thereby resulting in increased hepatic steatosis." (PMID 37834101, 2023). "Moreover, FTO inhibited the expression of PPARα, which may mediate its role in hepatic steatosis." (PMID 35282837, 2022). "Rescue of its levels prevents hepatic steatosis and NASH (non-alcoholic steatohepatitis) by increasing fatty acid oxidation through PPARα signaling." (PMID 36700214, 2022). "circRNA_0046366 and circRNA_0046367 are endogenous regulators of miR-34a, and they reduce hepatic steatosis by blocking the interaction of miR-34a and miRNA response element (MRE) located in PPARα mRNA." (PMID 35595755, 2022). "Thus, activating AMPK and PPARα may protect against hepatic steatosis and NAFLD development." (PMID 35628280, 2022). "We first investigated the effect of ATL I on hepatic steatosis, and our results showed that ATL I dose-dependently activated PPARα reporter activities." (PMID 36558977, 2022). "Feno significantly ameliorated the accumulation of various lipids in the plasma of VPA-induced hepatotoxic mice by activating PPARα, significantly reduced the plasma ACs concentration, and attenuated VPA-induced hepatic steatosis." (PMID 36425583, 2022). "The findings of our study demonstrate that SSC enhances fatty acid oxidation by activating PPARα-mediated gene transcription and increases CPT1 and ACOX1 activity, thereby counteracting hepatic steatosis." (PMID 35628280, 2022). "The present study showed that OLETF rats and OLETF-HFrD rats had significantly downregulated PPARα and CPT-1 expressions, leading to fatty liver pathogenesis." (PMID 33972568, 2021). "Similarly, the repression of SIRT1 in mouse liver is sufficient to induce hepatic steatosis, an effect that might be mediated by the key regulators of glycolysis and lipolysis, peroxisome proliferator-activated receptor (Ppar)-γ and Pparα as Sirt1 deletion impairs their function." (PMID 34069012, 2021). "Here, we found that PEG-BR reduced SCD1 and FAS while activating PPARα and ACOX1, improving hepatic steatosis in obese mice." (PMID 33390979, 2020). "PPARα, the main controller of fatty acid oxidation in the liver, is regulated by NIK during ALD, considering that PPARα agonists reversed NIK-mediated suppression of PPARα activity, reduction in fatty acid oxidation, and hepatic steatosis." (PMID 32206109, 2020).
Hepatic steatosis (continued). "Previous published studies have demonstrated an increased lipogenesis and a decreased fatty acid β-oxidation in hepatic steatosis and these processes are tightly controlled by a number of genes including CPT-1a and PARs such as PPARα." (PMID 33224240, 2020). "The findings of our study demonstrated that catalpol treatment enhanced fatty acid oxidation by activating PPARα-mediated gene transcription and improving CPT1 and ACOX1 activity, thereby attenuating hepatic steatosis." (PMID 32420361, 2020). "The inhibition of the AR/polyol pathway reduces fructose production and hepatic fat accumulation in high glucose diets as well as improved PPARα activity and enhanced FAO, thus attenuating liver steatosis in HFD-obese models." (PMID 32785059, 2020). "PPARα, the primary transcriptional controller of fatty acid oxidation, is a regulatory node of NIK, as PPARα agonists reverse NIK-mediated hepatic steatosis and malfunction of fatty acid oxidation." (PMID 32206109, 2020). "We propose that aging induces RAGE upregulation, which inhibits PPARα signaling and suppresses mitochondria‐related fatty acid β‐oxidation, eventually leading to excessive FFA production and then hepatic steatosis." (PMID 32936538, 2020). "Statin treatment decreases both hepatic steatosis and steatohepatitis by increase in hepatic mitochondrial and peroxisomal FAO via induction of PPARα and target genes." (PMID 33072455, 2020). "Here the authors show that GPS2 inhibits PPARα activity and that ablation of GPS2 ameliorates hepatic steatosis in mice." (PMID 30975991, 2019). "Intriguingly, these effects were gone in PPARα KO mice, demonstrating TBL1 and TBLR1 synergistically prevent hepatic steatosis and hypertriglyceridemia by regulating fatty acid oxidation genes in a PPARα-dependent manner." (PMID 31293521, 2019). "Meanwhile, alcohol-induced impairment of fatty acid oxidation via the inhibition of PPARα, which controls the expression of CPT1 and ACO, also plays a pivotal role in the progresssion of hepatic steatosis." (PMID 31906014, 2019). "Rescue of plasmalogen levels by alkyl glycerol treatment prevented hepatic steatosis and NASH through PPARα-dependent increase in fatty acid oxidation, suggesting a role for endogenous plasmalogen production in PPARα signaling." (PMID 28523433, 2018). "A recent report has indicated that PPARα also modulates the expressions of lipogenic genes in liver, such as ACC, which are closely related to fatty acid synthesis and oxidation in hepatic steatosis in HFD-fed animals." (PMID 30551559, 2018). "We detected the expression of these genes after treatment with PCB, PCBG, MPG, and the reference compound, QCT, which was reported to exert a preventive effect against hepatic steatosis probably through SIRT1/AMPK and PPARα pathways." (PMID 30154382, 2018). "Bio-informatic prediction of miR-21 potential mRNAs target revealed putative genes involved in both HCC and in Fatty Liver disease, including PTEN33, and SLC2A1 and PPARA that also showed reduced expression after sodium oleate treatment in dHepaRG cells." (PMID 30206377, 2018). "This circRNA-based gene therapy is proposed to induce the resolution of hepatic steatosis and lipid peroxidation in NAFLD patients via an impact on circRNA_0046367/miR-34a/PPARα axis." (PMID 29018509, 2017). "Activation of PPARα suppresses hepatic DNL and pro-inflammatory pathways that lead to insulin resistance, dyslipidaemia, and fatty liver." (PMID 29020051, 2017). "LPIN1 also serves as the coactivator of transcription factors (PPARα, PGC-1α), both of which take the central place during hepatic steatosis." (PMID 28717649, 2017). "The findings lead to introduction of an informative biomarker panel including INS, PPARA, LEP, SREBF1, and ALB proteins related to the fatty liver disease." (PMID 28224024, 2016). "Our data suggest that LJEE can prevent hepatic steatosis by reducing hepatic DGAT2 expression, as well as by inducing PPARα expression." (PMID 26506376, 2015).